CTLA4 (cytotoxic T-lymphocyte associated protein 4)
Diseases named in the same sentence as CTLA4 in open-access papers (continued):
Sharing a sentence is not in itself a finding about the gene and the disease.
Hepatic failure (5 papers, 2016 to 2025). "The results demonstrate that GPX3 drives pathogenic mechanisms in liver failure through oxidative stress-related pathways (e.g., collagen cross-linking, extracellular matrix remodeling) and immune dysregulation (e.g., macrophage activation, PD-1/CTLA-4 signaling)." (PMID 40276677, 2025). "Conversely, a recent study contradicted those findings, showing elevated GITR levels as well as PD-1 and cytotoxic T lymphocyte-associated antigen 4 (CTLA-4) levels in treatment-naïve chronic HBV patients and individuals with HBV-related hepatic failure." (PMID 39061246, 2024). "The study revealed an upregulation of immunosuppressive features, such as CTLA-4 and PD-1, on CD4+CXCR5−FOXP3+ T cells in treatment-naïve CHB patients and in patients with HBV-related hepatic failure compared to healthy controls." (PMID 37243227, 2023). "Of note, the levels of CTLA4 and GITR were significantly upregulated in patients with HBV-related hepatic failure." (PMID 36635631, 2023).
Hyponatremia (5 papers, 2015 to 2024). An abnormally decreased sodium concentration in the blood. "Symptoms of hypocortisolism are more frequent with anti-PD-1/anti-PDL-1 than with anti-CTLA-4: headache is rare, and hyponatremia is more prevalent." (PMID 33228219, 2020). "It is worth mentioning that hyponatremia may also occur, as it has been frequently reported in the case of pituitary inflammation during anti-CTLA-4 therapy." (PMID 34236546, 2021).
Insulin resistance (5 papers, 2012 to 2024). Increased resistance towards insulin, that is, diminished effectiveness of insulin in reducing blood glucose levels. "In diet-induced obese mice, treatment with CTLA4-Ig reduced body weight, improved insulin resistance and reduced adipose tissue inflammation by a mechanism involving adiponectin upregulation, M1 to M2 macrophage polarization, Treg stimulation, and TGF-β signaling." (PMID 31475003, 2019). "Here, we found genes related to insulin resistance and DM2 (PTPRF and CTLA4 altered in BSCL2mut; IGFBP4 altered in both CGL types)." (PMID 38755198, 2024).
invasive breast carcinoma (5 papers, 2018 to 2025). A carcinoma that infiltrates the breast parenchyma. "According to the analysis of TIMER data, PIMREG expression showed a relatively strong positive correlation with CTLA-4 only in BRCA (invasive breast carcinoma)." (PMID 37483962, 2023). "Fewer than 4% of the invasive breast carcinomas are positive for PD-L1 expression which proposes that CTLA-4 is a more important immune checkpoint marker in the breast tissue." (PMID 29672601, 2018).
ischemic stroke (5 papers, 2014 to 2025). A stroke disorder caused by obstruction of blood flow to the brain, due to thrombotic (local blood clot formation) or embolic (due to a blood clot or other material traveling from another site) event. "Thus, it appeared as though the molecules of the CD80/CD28, CTLA-4, and the PD-1/PD-L pathway are more critical than others in ischemic stroke." (PMID 25157219, 2014). "Following ischemic stroke, T cells upregulate activation markers, which are not controlled due to disturbed upregulation of negative feedback loops; one such example is cytotoxic T-lymphocyte-associated protein (CTLA)-4." (PMID 41373643, 2025).
leprosy (5 papers, 2018 to 2024). Leprosy is a chronic infectious disease affecting primarily the skin and peripheral nervous system. "It deduces that through raising the expression of Cbl-b, a member of mammalian Cbl family proteins (ubiquitin ligases thought to negatively regulate TCR signaling), the overexpression of TGF-β and CTLA4 causes T cell hyporesponsiveness, a significant leprosy characteristic." (PMID 39308868, 2024). "In the immunosuppressive environment like leprosy, upregulation of inhibitory molecules such as cytotoxic T-lymphocyte-associated antigen-4 (CTLA-4) and programmed cell death-1 (PD-1) on T cells and their ligands on APCs which resemble T-cell anergy and exhaustion in leprosy patients." (PMID 30083152, 2018). "In several studies, Treg cells have been demonstrated to suppress immune responses in the periphery of leprosy patients and markers associated with Treg cells, mostly CD25, TGF-1, IL-35, CTLA4, IL-10, and FoxP3." (PMID 37153623, 2023). "A higher number of Tregs were observed in leprosy patients, who expressed increased levels of IL-10 and CTLA-4 but not TGF-β." (PMID 37153623, 2023). "Viera e collaborators also observed that CTLA-4 does not participate as a suppressor molecule in multibacillary leprosy patients." (PMID 35924037, 2022). "When comparing leprosy patients to HHC, 16 genes showed significantly different expression for leprosy patients (increased: FCGR1A, IL6, IL15, LRKK2, MBP, MSR1, PACRGv1, TLR1, TLR4; decreased: CAMTA, CD3E, CTLA4, CXCL13, GATA3, LAG3, TFGB)." (PMID 31784594, 2019).
liposarcoma (5 papers, 2018 to 2026). A usually painless malignant tumor that arises from adipose tissue. "In this study, immune-high group (mainly UPS and liposarcoma) exhibited high expression of PD1, PDL2, and CTLA-4." (PMID 33789622, 2021). "This study will help define the role of single agent anti-PD1 and combination anti-CTLA4 and anti-PD1 therapy in patients with surgically resectable dedifferentiated liposarcoma and undifferentiated pleomorphic sarcoma." (PMID 30249211, 2018).
neutropenia (5 papers, 2012 to 2025). A decrease in the number of neutrophils found in the blood. "In terms of hematologic toxicity, both the Chemo + PD-1 regimen (RR, 1.65; 95%CI, 1.25–2.2) and the Chemo + PD-L1 regimen (RR, 1.58; 95%CI, 1.19–2.12) exhibited a higher risk of severe neutropenia compared with the Chemo + CTLA-4 regimen." (PMID 40783512, 2025). "Additionally, the Chemo + PD-L1 + CTLA-4 regimen was associated with the highest probability of experiencing grade ≥ 3 TRAEs (SUCRA = 0.98) and neutropenia (SUCRA = 0.90)." (PMID 40783512, 2025).
pituitary adenomas (5 papers, 2021 to 2025). "Some recent studies employing RNAscope found mRNA expression of programmed death ligand 1 (PD-L1) and cytotoxic T lymphocyte-associated protein 4 (CTLA4) in pituitary adenomas." (PMID 38756997, 2024). "Combined immunotherapy (anti-PD-L1 and CTLA-4) for aggressive pituitary adenomas is still in phase 2 (Memorial Sloan Kettering cancer center, United States, NCT04042753)." (PMID 36831707, 2023). "PD-1, PD-L1, and CTLA-4 expression have been demonstrated in pituitary adenomas to varying degrees." (PMID 40806825, 2025). "In this study, we have found that the mRNA expression levels of the ligands for immune checkpoint receptors PD-1 and CTLA-4—namely, PD-L1 and PD-L2; CD80 and CD86, respectively— were all significantly higher in pituitary adenomas than in the normal human pituitary." (PMID 34745002, 2021). "The significance of increased CD80 and CD86 expression in pituitary adenomas has not been previously reported, but we hypothesize it predicts an increased reliance on CTLA-4 mediated pathway of tumor suppression." (PMID 34745002, 2021).
pituitary tumor (5 papers, 2019 to 2023). A benign or malignant neoplasm affecting the pituitary gland. "The increased expression of immune checkpoints, such as the programmed death ligand-1 (PD-L1) and the cytotoxic T-lymphocyte-associated protein 4 (CTLA-4) ligands CD80 and CD86, has been associated with aggressiveness in proliferative pituitary tumors." (PMID 37958702, 2023). "CTLA-4 inhibitors are used in combination with PD-1/PD-L1 inhibitors in the treatment of pituitary tumors reported so far." (PMID 34447484, 2021). "At the same time, it is also a kind of evidence of the therapeutic effect of CTLA-4 antibody on pituitary tumors." (PMID 34447484, 2021). "While anti-programmed cell death protein 1 (anti-PD-1) and anti-cytotoxic T-lymphocyte-associated protein 4 (anti-CTLA4) antibodies have been extensively used to target immune checkpoints in many cancers, their use in pituitary tumors has just commenced." (PMID 34090476, 2021). "Currently, CTLA-4 has been rarely reported in pituitary tumors." (PMID 34447484, 2021). "Our patient did not benefit from mutational analysis nor CTLA-4 or PD-L1 IHC, as the surgical resection of his pituitary tumor was performed at a different medical center and the remaining anatomic-pathological samples were of insufficient quality." (PMID 33112279, 2021).
polyendocrinopathy (5 papers, 2020 to 2022). "Ipilimumab monotherapy or the combined therapy of anti-CTLA-4 and anti-PD-1 resulted in the highest risk of polyendocrinopathies, including PAI, followed by anti-PD-1 monotherapy, which was consistent with other researchers." (PMID 35870109, 2022).
primary biliary cirrhosis (5 papers, 2014 to 2024). "The CTLA4 haplotype (rs231775-rs231777-rs3087243-rs231725; G-C-G-A) was a protective factor for progression of primary biliary cirrhosis in Japanese patients." (PMID 38723011, 2024). "A specific TNF–alpha variant is only associated with an altered risk of primary biliary cirrhosis when there is an AA genotype, not AG or GG, at the − 318 CTLA4 promoter polymorphism." (PMID 32835228, 2020).
prostate adenocarcinoma (5 papers, 2017 to 2025). "The immune checkpoints PD-1, PD-L1, and CTLA4 were positively correlated with AATF expression in bladder urothelial carcinoma (BLCA), kidney chromophobe (KICH), and prostate adenocarcinoma (PRAD)." (PMID 36275893, 2022).
rhabdomyosarcoma (5 papers, 2020 to 2025). A rare aggressive malignant mesenchymal neoplasm arising from skeletal muscle. "Literature on the use of PD‐1 inhibitors in rhabdomyosarcoma is limited to one trial of combination therapy with PD‐1 and CTLA‐4 inhibitors, which found a clinically significant sustained partial response in 1 of 7 pediatric patients with alveolar rhabdomyosarcoma." (PMID 40090763, 2025).
Splenomegaly (5 papers, 2009 to 2023). Abnormal increased size of the spleen. "The mice with specific deficiency of CTLA-4 in Tregs developed spontaneous systemic lymphoproliferation, severe splenomegaly, suggesting CTLA-4 exerts a crucial role in maintaining self-tolerance." (PMID 36810034, 2023).
stomach cancer (5 papers, 2016 to 2025). "Compared with benign tissues, the CTLA4 and ENTPD2 were highly expressed in gastric tumor tissues, while the AKR1B1, CLDN6, EMB, GPR15 and VWF were highly expressed." (PMID 37066015, 2023).
thyroid tumor (5 papers, 2021 to 2025). A benign or malignant neoplasm affecting the thyroid gland. "We aimed to evaluate CTLA-4 and PD-L1 immunoexpression in thyroid tumours and correlated them with clinicopathological parameters." (PMID 39286684, 2024). "We evaluated the tumour proportion scores (TPSs) and immune proportion scores (IPSs) for CTLA-4 and PD-L1 immunoexpression in thyroid tumours and correlated them with clinicopathological parameters." (PMID 39286684, 2024). "Further investigation into new strategies aside from anti-cytotoxic T-lymphocyte antigen 4 (CTLA-4)/programmed death 1 (PD-1)/PD-L1 antibodies, validation of predictive biomarkers, and better population selection for clinical trials in thyroid neoplasms is more than needed in the near future." (PMID 35992118, 2022). "Besides the direct involvement of BRAFV600E in thyroid tumor initiation and dedifferentiation, previous studies have reported an association of PTC with an immunosuppressive signature at mRNA level, as evidenced by the induction of the CTLA-4, PD-L1, and HLA-G genes." (PMID 37569841, 2023). "Several studies already described an abundant presence of immune cells in BRAF V600E positive thyroid tumors with more aggressive behavior, as well as higher expression of immune evasion genes such as PD-L1, IDO1, and CTLA-4." (PMID 34680332, 2021). "CTLA-4 (UMAB249) and PD-L1 (SP263) expression were assessed in all the cases of thyroid tumours." (PMID 39286684, 2024).
type 2 diabetes (5 papers, 2019 to 2023). "The patients with melanoma were treated with anti-PD-1 or anti-CTLA-4, which increased part of the patients’ glycemia levels and caused T1D and type 2 diabetes (T2D) during the immunotherapy period." (PMID 37497212, 2023). "Oncological patients treated with combination therapy of anti-PD-1 and anti-CTLA-4 can develop a particular pattern of T1DM, with very rapid onset within a few weeks after starting ICI therapy, even in the presence of an existing type 2 diabetes." (PMID 31870373, 2019).
acute kidney injury (4 papers, 2016 to 2025). Sudden and sustained deterioration of the kidney function characterized by decreased glomerular filtration rate, increased serum creatinine or oliguria. "We examined the relations between CTLA-4 SNPs (rs733618, rs4553808, rs5742909, rs231775 and rs3087243) and eGFR (eGFR < 90 mL/min/1.73 m2 was identified as renal failure and was staged according to the KDIGO guidelines) over a period of 60 months in recipients of kidney transplants." (PMID 27081086, 2016). "For instance, the CheckMate-069 trial combined Ipilimumab 3 mg/kg (anti CTLA-4) with Nivolumab 1 mg/kg and reported a proportion of 1:1000 cases of renal failure of grade 1-2 while Ipilimumab 3 mg/kg or Nivolumab 3 mg/kg alone reported 0:1000 and 2:1000 cases of renal failure respectively." (PMID 28105370, 2017).
alveolitis (4 papers, 2014 to 2022). "On the one hand, it could have a direct effect on lung inflammation, since experimental studies have shown CTLA-4 to play a major role in lung inflammation in other lung diseases, such as hypersensitivity pneumonitis." (PMID 35884786, 2022).
autoimmune enteropathy (4 papers, 2018 to 2025). Severe-immune mediated enteropathy describes a variety of intestinal disorders that can range from a serious, early-onset systemic disease (IPEX) to a mild isolated gastrointestinal disease. "CTLA4 haploinsufficiency is implicated in autoimmune enteropathy, primarily through dysregulated T-cell activity, culminating in sustained inflammation and tissue destruction in the small intestine." (PMID 40724600, 2025). "Genetic testing is crucial in identifying CTLA4 haploinsufficiency, which often underlies autoimmune enteropathies." (PMID 40724600, 2025). "For example, monogenic disorders like CTLA4 haploinsufficiency, which contribute to autoimmune enteropathy, are increasingly identified through genetic testing, allowing precise diagnoses in refractory or atypical cases." (PMID 40724600, 2025). "Autoimmune enteropathy is more common in LRBA deficiency, while autoimmune cutaneous disorders are seen more frequently in CTLA4 haploinsufficiency." (PMID 36788146, 2023).
autoimmune lymphoproliferative syndrome type V (4 papers, 2018 to 2022). "This variant has not previously been reported, but other truncating variants in CTLA4 are known to be causative for autoimmune lymphoproliferative syndrome type 5 (ALPS5, OMIM 616100) by way of haploinsufficiency." (PMID 35743704, 2022). "Recently, heterozygous CTLA4 loss-of-function mutations (CTLA4wt/mut) were identified in autoimmune lymphoproliferative syndrome type V patients (ALPS5; OMIM #616100)." (PMID 30087679, 2018). "Although their clinical phenotype, multi-organ inflammatory disease, is superficially similar to that of CTLA4 haploinsufficient autoimmune lymphoproliferative syndrome type V (ALPS5) patients, we demonstrate our subjects’ underlying immunopathology to be distinct." (PMID 30087679, 2018).
brain cancer (4 papers, 2016 to 2024). A primary or metastatic malignant neoplasm affecting the brain. "The survival rates of brain cancer in mice treated with anti-CTLA-4 and anti-PD-1 monotherapy were 40% and 60%, respectively, whereas the survival rate was up to 78% when the two were combined." (PMID 39249163, 2024). "Nevertheless, our findings imply that depleting antibodies dependent upon FcγR interactions, such as anti-CTLA-4 or anti-OX40, may not be of clinical value in brain cancer if the appropriate FcγR are also absent from human microglia." (PMID 27190629, 2016).
brain glioma (4 papers, 2019 to 2023). A malignant glioma that involves the brain. "Brain glioma treatment with checkpoint inhibitor antibodies to cytotoxic T-lymphocyte-associated antigen 4 (a-CTLA-4) and programmed cell death-1 (a-PD-1) was largely unsuccessful due to their inability to cross blood–brain barrier (BBB)." (PMID 31462642, 2019). "A study in brain glioma patients indicated that CTLA-4 is highly expressed on T cells, specifically the effector CD4 + T cells." (PMID 34006227, 2021). "The lowest CTLA4-expressing cancer type is low grade glioma of the brain (LGG)." (PMID 31991588, 2020). "However, the significance of soluble CTLA-4 (sCTLA-4) remains unclear in the patients with brain glioma." (PMID 34006227, 2021). "However, no investigation is reported about the soluble CTLA-4 levels in blood circulation of the patients with brain glioma that is the most common type among primary tumors in central nervous system with rapid growth and poor prognosis." (PMID 34006227, 2021).